SMAD3 (SMAD family member 3)
Diseases named in the same sentence as SMAD3 in open-access papers (continued):
Sharing a sentence is not in itself a finding about the gene and the disease.
tumor (continued). "Smad3 is a critical transcription factor for the TGF‐β1 signaling pathway in tumor pathogenesis and contributes to cell growth, apoptosis, invasion and metastasis." (PMID 30761253, 2019). "TRIB3 binds SMAD3 to promote tumor cell migration and invasion and activates MAPK and TGFβ pathways." (PMID 29757932, 2018). "It has been shown that high expression of SMAD3 is essential for the tumor suppressive effects of TGF‐β, while lower expression levels are associated with the tumor‐promoting effect of TGF‐β." (PMID 29130642, 2018). "Double immunofluorescence against β-catenin and phospho-SMAD3 revealed the activation of the TGFβ pathway in tumour cells and reactive tissue." (PMID 29541918, 2018). "Recent data have indicated that Smad3 functions as a tumour suppressor by inhibiting cell proliferation and promoting apoptosis." (PMID 29449642, 2018). "It has been well established that TGFβ regulates EMT during tumor metastasis by controlling the expression of Smad3-mediated target genes." (PMID 30258109, 2018). "Consistent with the tumour-suppressive function of SMAD3, transient overexpression of SMAD3 led to a significant 30% reduction in the 3D outgrowth of MDA-231 cells." (PMID 30318519, 2018). "The results revealed that the expression levels of p-Smad2, p-Smad3 and p-c-Myc in the PIM1-deficient tumour edge tissues were significantly lower than those in the control tumour edge tissues." (PMID 29472550, 2018). "Smad3 has been reported to promote tumor progression at advanced stages by inducing EMT and enhancing pro-metastatic transcription factors such as Snail and Slug." (PMID 29874844, 2018). "The closely clustered SMAD2/3 Nuclear Pathway contains SMAD3 which regulates expression of angiogenic molecules in tumor cells and vascularization in tumor lesions." (PMID 29554099, 2018). "SMAD3 expression has been shown to regulate the switch TGF-β signaling pathway between tumor suppressive or oncogenic effects in cancer." (PMID 30761216, 2018). "For example, BMP-3b selectively activates TGF-β receptor (TGF-βI/II)-dependent Smad3 phosphorylation and attenuates tumor formation." (PMID 29922215, 2018). "Deletion or inhibition of Smad3 in the tumour microenvironment suppresses tumour growth, invasion and metastasis in two syngeneic mouse tumour models." (PMID 28262747, 2017). "Overexpression of miR-1 mimics significantly decreased tumor glycolysis, including lactate production and glucose uptake, and cell proliferation, and these effects were reversed by ectopic expression of Smad3." (PMID 28471448, 2017). "Tumour progression was significantly reduced in mice whose peritoneal Smad3 expression had been knocked down as compared with controls." (PMID 28247413, 2017). "It is suggested that TGF-β1-mediated pro-tumorigenic microenvironment can be shifted into a tumour-suppressive one by targeting the Smad3-dependent tumour microenvironment." (PMID 28262747, 2017). "We demonstrated an enhanced anticancer effects of Smad3−/− NK cells in cancer progression whereby mice infused with Smad3−/− NK1.1+ cells displayed reduced tumour growth compared with Smad3+/+ NK1.1+ cell-recipient mice." (PMID 28262747, 2017). "TGF-β has a supportive role in progression of established tumour and Smad3 is a key mediator in the canonical TGF-β signalling pathway." (PMID 28262747, 2017). "The ability of adoptive transfer of E4BP4 knockdown Smad3−/− NK cells to reverse the suppressive effect of Smad3−/− NK cells on tumour growth in B16F10 tumour-bearing NOD/SCID mice revealed the specific role of E4BP4 in NK cell-mediated antitumour activities." (PMID 28262747, 2017).
tumor (continued). "In this study, we demonstrated that downregulated miR-323a-3p due to IG-DMR methylation functioning as a tumor suppressor inhibited the epithelial–mesenchymal transition (EMT) progression by regulating MET/SMAD3/SNAIL circuit." (PMID 28837140, 2017). "Increase in production and anticancer activities of NK cells but decrease in angiogenesis, Treg response and tumour-invasive activities were found in the Smad3-knockout or -inhibited tumour-bearing mice." (PMID 28262747, 2017). "However, the use of anti-NK1.1 antibody may also deplete NKT cells; therefore, the specific role of Smad3 in NK cell production was further examined by adoptive transfer of Smad3−/− or Smad3+/+ NK cells (NK1.1+) into the tumour-bearing NK cell deficiency mice (NOD/SCID)." (PMID 28262747, 2017). "Here, we have knocked down Smad3 in the peritoneums of mice, resulting in reduced intraperitoneal tumour growth and metastases." (PMID 28247413, 2017). "During the first week after subcutaneous inoculation of LLC-luc cells, we observed almost equal tumour growth in both Smad3−/− and Smad3+/+ mice." (PMID 28262747, 2017). "In this study, we investigate the actions of phospho-Smad3 Ser213 on miR-1 mediation of tumor glycolysis." (PMID 28471448, 2017). "Cells expressing the miR-1 mimic generated smaller tumors than control group and those overexpressing Smad3, indicating miR-1 suppressed, while Smad3 promote tumor proliferation in vivo." (PMID 28471448, 2017). "We identified HIF-1α is a direct target of miR-1, and most important, Smad3 regulated and interacted with HIF-1α, leading to increasing Smad3 activity, which implies the contribution of a feed forward loop in regulation of tumor glycolysis and proliferation." (PMID 28471448, 2017). "Studies carried out in tumor cell lines have shown that Dkk-3 enhanced phosphorylation of Smad3, a molecule that lies along the signaling pathway activated by TGF-β1." (PMID 28352232, 2017). "In this investigation, to explore a potential role for PRAJA in tumorigenesis, we conducted a genomic analysis of Praja1 (PJA1), Praja2 (PJA2) and Smad3 across 29 tumor types." (PMID 28966725, 2017). "MiR-1 suppressed aerobic glycolysis and tumor cell proliferation via inactivation of Smad3 and targeting HIF-1α, leading to reduce HK2 and MCT4 expression, which illustrated a novel pathway to mediate aerobic glycolysis in cancer cells." (PMID 28471448, 2017). "We also demonstrated that suppression of tumor glycolysis by the miR-1/Smad3 axis was critical for inhibition of tumor cell proliferation in vivo." (PMID 28471448, 2017). "Smad3−/− bone marrow gives rise to an expanded NK cell population with enhanced tumour-suppressive activities in vivo, and promotes differentiation of NK cells ex vivo." (PMID 28262747, 2017). "We demonstrated that Smad3 is an important checkpoint for TGF-β-mediated cancer progression in the tumour microenvironment." (PMID 28262747, 2017). "Remarkably, Dkk-3 is able to up-regulate ATF3 and enhance Smad3 phosphorylation in tumor cell lines." (PMID 28352232, 2017). "Linker phosphorylated Smad2/3 promotes oncogenesis, while C-terminal phosphorylation of Smad3 tend to produce tumor suppression." (PMID 29156696, 2017). "To conclude, microRNA-21 promotes tumor progression in a MAPK-dependent manner while microRNA-145 suppresses it via domain-specific phosphorylation of Smad3 in HCC." (PMID 29156696, 2017). "We found that genetic deletion or pharmacological inhibition of Smad3 significantly enhanced the production of NK cells (NK1.1+/NKp46+ cells) locally in the tumour microenvironment and systemically in the peripheral blood and splenic tissue." (PMID 28262747, 2017). "We then investigated the origin of Smad3-dependent tumour microenvironment by using GFP+ Smad3−/− and GFP+ Smad3+/+ bone marrow chimeric mice bearing subcutaneous LLC-luc or B16F10-luc tumours." (PMID 28262747, 2017).
tumor (continued). "In conclusion, Smad3-dependent tumour microenvironment plays a crucial role in cancer growth, invasion and metastasis." (PMID 28262747, 2017). "In the present study, we demonstrate the crucial role of Smad3-dependent tumour microenvironment in cancer progression by using two well-established syngeneic mouse tumour models." (PMID 28262747, 2017). "Mice with 4T1 OCIB showed higher SMAD3 phosphorylation, indicative of TGFβ signaling, compared to non-tumor control mice." (PMID 29312148, 2017). "Studies have revealed tumorigenic function of activin-responsive SMAD3 and tumor suppressive roles of inhibins and BMPs in the gonad." (PMID 29221447, 2017). "Compared with GFP+ Smad3+/+ chimeric mice, mice with GFP+ Smad3−/− bone marrow exhibited significant reduction in the tumour growth and mortality rate, which was again associated with a 10-fold increase in GFP+ NK1.1+ cells in the tumour microenvironment." (PMID 28262747, 2017). "Here we report an additional role of Smad3 in the tumour microenvironment regulating cancer progression." (PMID 28262747, 2017). "We demonstrated that the enhanced NK cell-mediated anticancer immunity has an important role in the anticancer effects of Smad3-dependent tumour microenvironment targeted treatment." (PMID 28262747, 2017). "Noticeably, NOD/SCID mice that received Smad3−/− NK cells showed a greater inhibition of tumour growth compared with those that received Smad3+/+ NK cells." (PMID 28262747, 2017). "Overexpression of Smad3 significantly reversed the inhibition of miR-1-mediated tumor glycolysis and tumor growth." (PMID 28471448, 2017). "Smad3 functions as a transcriptional modulator activated by transforming growth factor-beta and plays dual roles as tumor suppressor and tumor promoter in HCC, which is context-specific." (PMID 27110775, 2016). "Since we did not observe a comparable effect in wild type mice, the results suggest that VD tumor suppression is modulated by aberrant Smad3/TGF-β signaling." (PMID 27456065, 2016). "Our investigations indicated that miR-142-5p is highly and differentially expressed in some tumor cells, indicating that miR-142-5p functions an oncogenic role by suppressing the translation of SMAD3 to promote cancer cell growth." (PMID 27683030, 2016). "Because nuclear hetero-oligomerization is essential to the assembly of target-specific transcriptional complexes, Smad3 can utilize two different phospho-domains to transmit different signals, as both a tumor suppressor and a tumor promoter." (PMID 26771649, 2016). "DROSHA-rs10719 and SMAD3-rs17228212 had an opposite detrimental effect on pathological tumour response (p=0.0274, p=0.0049)." (PMID 26934318, 2016). "IL-37b potentially possesses the efficiency to suppress HCC growth, at least in part, through the conversion of Smad3 phospho-isoform signaling from JNK/pSmad3L/c-Myc oncogenic signaling to pSmad3C/p21 tumor-suppressive signaling." (PMID 27835881, 2016). "We conclude that VDD promotes tumor growth in the context of Smad3 disruption, potentially through regulation of TLR7 expression and β-catenin activation." (PMID 27456065, 2016). "Smad3, a target of miR-206 or miR-140, has a role in tumor cell metastasis and E-cadherin and α-SMA12 expression, so we measured these proteins in miR-206- (or miR-140)-treated A549 cells." (PMID 28005074, 2016). "In vivo, silencing of Smad3 dramatically reduced both the volume and number of pan-cytokeratin-positive tumor cells detected in the lymph nodes of the inoculated mice." (PMID 26646322, 2016). "The use of DMBA-induced mammary tumorigenesis is primarily relevant from the standpoint of the role of Smad3 as a tumor suppressor." (PMID 27588495, 2016).
tumor (continued). "Mechanistically, we determined that IL-37 promoted Smad3 phospho-isoform signaling conversion from JNK/pSmad3L/c-Myc oncogenic signaling to pSmad3C/p21 tumor-suppressive signaling." (PMID 27835881, 2016). "Our analyses of VD deprivation (VDD) in in vivo models of liver tumor formation revealed striking three-fold increases in tumor burden in Smad3+/− mice, with a three-fold increase in TLR7 expression compared to controls." (PMID 27456065, 2016). "Specifically, we observed that the tumor burden increased over three-fold and the liver-to-body weight ratio was significantly higher in Smad3+/− mice deprived of VD compared to Smad3+/− animals treated with high-dose VD." (PMID 27456065, 2016). "Further study demonstrated that the expression of MUC1 is consistent with that of pSmad3L and c-Myc but inverse to that of pSmad3C and p21WAF1, suggesting that MUC1 shifted Smad3 signaling from tumor-suppression to oncogenesis in tumor cells." (PMID 25714018, 2015). "The transcriptional regulator SMAD3 is both a tumor suppressor and a vital mediator of TGF-β-mediated immune suppression, which likely contributes to the process bridging UC to CRC through targeting growth-related proteins." (PMID 26461477, 2015). "Here, we show that KLF17 plays an integral role in potentiating TGF-β/Smad signaling via Smad3-dependent pathway to suppress tumor progression." (PMID 25766320, 2015). "Halofuginone inhibited TGFβ-dependent Smad3 phosphorylation, causes reduction in fibroblasts differentiation, reduction in the levels of ECM proteins and inhibition of fibrosis and tumor growth." (PMID 25569515, 2015). "Activated TβRI and JNK differentially phosphorylates the mediator Smad3 to become pSmad3C (Ser-423/425) and pSmad3L (Ser-213) and then transmits tumor-suppressive or oncogenic TGF-β signaling, respectively, by mediating distinct transcriptional responses." (PMID 25714018, 2015). "Several studies reported that inflammatory cytokines activate JNK, resulting in the switch in Smad3 signaling from tumor-suppression to oncogenesis." (PMID 25714018, 2015). "Genotyping of tumor samples confirmed the integration of Rif1 shRNA in the teratoma cells produced by Rif1 shRNA-transduced Smad3−/− ESCs." (PMID 25569105, 2015). "Other studies demonstrated that ectopic expression of miR-106b inhibited the expression of P21, RB and Smad3 participated in the regulation of G1-to-S cell cycle transition, thereby leading to excessive proliferation and tumor development." (PMID 26053181, 2015). "TGFβ/Smad3 signals play a critical role in the regulation of tumor progression including metastasis." (PMID 25980442, 2015). "Our previous study found that MUC1 gene silencing inhibited the growth of SMMC-7721 cells in vitro and in vivo, and MUC1 shifted Smad3 signaling from a tumor-suppressive to an oncogenic function in MUC1-overexpressing HCC cells." (PMID 26057631, 2015). "Smad3 as a central mediator for the classical pathway of TGF-β signaling mainly transmits tumor-suppressive signaling." (PMID 25714018, 2015). "Collectively, these results indicate that MUC1 shifts Smad3 signaling from a tumor-suppressive pSmad3C/p21WAF1 to an oncogenic pSmad3L/c-Myc pathway by directly activating JNK in HCC cells, suggesting that MUC1 is an important target for HCC therapy." (PMID 25714018, 2015). "By immunohistochemical and western blot analyses, we found that Smad3 and p-Smad3 levels were negatively correlated with tumor invasion." (PMID 24636138, 2014). "Because nuclear hetero-oligomerization is essential to assembly of target-specific transcriptional complexes, Smad3 can utilize 2 different phospho-domains to transmit different signals, as both a tumor suppressor and a tumor promoter." (PMID 25050845, 2014). "TGF-β-driven tumor suppression was highly dependent on Smad3, and Smad3 target genes that were specifically enriched for involvement in tumor suppression were identified." (PMID 24890385, 2014).
tumor (continued). "And we know, TGF-β/Smad3 signaling has been regarded as tumor suppressor during tumor progression since TGF-β-induced CDKN1A (P16) and CDKN2B (P15) expression is correlated with tumor inhibition." (PMID 24427302, 2014). "During HCV-related carcinogenesis, JNK-activated chronic inflammation confers a selective advantage on preneoplastic hepatocytes by shifting Smad3 signaling from the tumor-suppressive pSmad3C to the oncogenic pSmad3L pathway." (PMID 25050845, 2014). "Our demonstration of the occurrence of a SMAD3 dependent EMT in the epithelial cancer cell lines advocates for a role of EC-MPs in tumor plasticity." (PMID 24424657, 2014). "In tumor cells, SMAD3/SMAD4 mediates transcription of SNAIL and SLUG, two master regulators of the EMT process." (PMID 24756567, 2014). "First, we compared patterns of TGF-β-regulated expression of Smad3 target genes in vitro, reasoning that genes that were regulated in M3 only should be enriched for Smad3-driven tumor-suppressive responses." (PMID 24890385, 2014). "Alternatively, galectin-7 mediates the nuclear export of Smad3 through complex formation, which is essential for the tumor-suppressive effects of hepatocyte growth factor on the transforming growth factor-beta signaling pathway." (PMID 24515895, 2014). "TGF-β/Smad3 effects on cell proliferation, differentiation and ephrin signaling contributed to the observed tumor suppression." (PMID 24890385, 2014). "On the other hand, HBx oncoprotein participates directly in hepatocarcinogenesis by shifting hepatocytic Smad3-mediated signaling from tumor suppression to oncogenesis in patients with chronic hepatitis B infection." (PMID 25050845, 2014). "While ANGPTL4 was upregulated by TGF-β in both MDA-MB-231 and M3 cells in vitro, we found that ANGPTL4 was actually downregulated by TGF-β/Smad3 in vivo in the M3 tumors where TGF-β functions as a tumor suppressor." (PMID 24890385, 2014). "CCNE1 and SMAD3 were strongly stained in the tumor tissues but were weak in the normal tissues, whereas the ALDH2 staining showed the reverse pattern." (PMID 25408144, 2014). "Our results confirmed the activation of the Smad3/TGFβ pathway, showing a strong increase in 12xSBE:mCherry expression rising at 16 wpf both in tumor mass (eGFP-KRASG12D-positive cells) and stromal microenvironment (eGFP-KRASG12D-negative cells)." (PMID 24878567, 2014). "Our data strongly suggest that the shift between tumor suppressive and tumor promoting TGF-β effects involves different regulation of Smad3 dependent transcription, TβRI expression, Smad2 signaling duration, and endogenous TGF-β/Smad7/TβRII levels." (PMID 23991075, 2013). "Two Smad3−/− animals in this study lived long enough to develop invasive neoplasia; one tumor was found in an animal necropsied 4 weeks post DSS treatment and the other animal survived to 27 weeks and also developed tumors." (PMID 24244446, 2013). "Real time PCR was used to measure mRNA expression of Smad2 and Smad3 in cancer and surrounding non-tumor tissue." (PMID 22539990, 2012). "EMT-like and TGFβ-pathway signatures, correlated with constitutive Smad3 signaling, also characterized Amela tumor cells." (PMID 23173060, 2012). "Inhibition of tumor invasion by stroma cells was achieved with halofuginone, an inhibitor of TGFβ/Smad3 signaling, alone or in combination with chemotherapy." (PMID 22848627, 2012). "Halofuginone that inhibited Smad3 phosphorylation reduced the number of host cells invading the tumor, collagen biosynthesis, and tumor growth." (PMID 22848627, 2012). "We also showed that p21 and p/CAF regulate TGFβ transcriptional activity on multiple tumor-promoting target genes by controlling Smad3 acetylation and Smad3 occupancy on its DNA binding elements." (PMID 22995475, 2012). "SMAD3 and SMAD4 are the key signaling proteins of the transforming growth factor-β (TGF-β) pathway and have been implicated to have tumor suppressive effects in the pathogenesis of breast and other cancer types." (PMID 21835029, 2011).